STIM1 (stromal interaction molecule 1)
Diseases named in the same sentence as STIM1 in open-access papers (continued):
Sharing a sentence is not in itself a finding about the gene and the disease.
cancer (continued). "Roles for STIM-1 in Ca2+ entry mechanisms have been highlighted in a range of pathophysiological processes including infection and cancer." (PMID 32098295, 2020). "Cancer progression has been reported to have up-regulation of stromal interaction molecule 1 (STIM1) in highly invasive CRC tissues and cell lines, as well as the promotion of metastasis in-vitro, and in-vivo." (PMID 33381452, 2020). "In cancer cells, the major calcium influx pathway is through store-operated calcium channels, which are composed by STIM1 and Orai1." (PMID 33348924, 2020). "In primary cancer samples, as well as in cancer cell lines, the total amount of STIM1 correlates with augmented migration and proliferation rates, and consequently with poor prognosis." (PMID 32916960, 2020). "As STIM1 and Orai1 over-expression has been observed across a multitude of malignancies, they are inarguably among the most enticing drug targets in anti-cancer therapy." (PMID 32599788, 2020). "Tumor expression of Orai1 and STIM1 have substantial implications for the adverse prognosis of cancer patients." (PMID 31252656, 2019). "Again, the significantly higher proliferation rate observed with STIM1-OE cells over that of EpCAM(+)CD133(+) cells overexpressing both STIM1 and Orai1 (present data) confirms the poor prognosis of several cancer types with overexpressed STIM1." (PMID 31366337, 2019). "The functional importance of STIM1/Orai1-mediated SOCE in cancer cell proliferation was extensively studied." (PMID 31252656, 2019). "As knowledge on the importance of SOCE in tumor biology and cancer progression accumulates, the blockade of STIM1/Orai1-dependent Ca2+ signaling has emerged as the potential and plausible targets for cancer therapeutics." (PMID 31252656, 2019). "Many studies demonstrated the importance of SOCE in the apoptosis of cancer cells, but the specific roles of STIM1 and Orai molecules are controversial." (PMID 31252656, 2019). "Over the last decade, accumulating evidence has suggested that STIM1, in association with Orai1-mediated SOCE, is involved in cancer progression by regulating cellular motility to affect focal adhesion turnover." (PMID 31464639, 2019). "Emerging studies demonstrated the importance of STIM1/Orai1-mediated SOCE in the context-dependent roles of autophagy in human cancers." (PMID 31252656, 2019). "This conclusion is consistent with previous reports that showed a correlation between cancer progression and STIM1 expression." (PMID 31506588, 2019). "The aim of the present study was to investigate the role of STIM1 in the regulation of cancer progression and its clinical relevance." (PMID 31564210, 2019). "Several studies have explored optimistic possibilities of targeting STIM1 and Orai1-mediated Ca2+ signaling in cancer cells, as well as vascular endothelial cells, for therapeutics." (PMID 31252656, 2019). "Targeting of either STIM1 or SOCE or both also influenced the sensitivity of cancer to different chemotherapeutic drugs." (PMID 30544747, 2018). "We focussed on mCRC cells for the following reasons: 1) metastasis is the leading reason for mortality in cancer patients and 2) Stim1 and Orai3 proteins were up-regulated in mCRC cells." (PMID 30123430, 2018). "Recently, several studies have indicated a role for Orai1 and STIM1 in migration of different types of cancer and non-cancer cells." (PMID 29507531, 2018). "STIM1 protein has been found to be elevated in several human cancer cells including in GBM where STIM activity is essential for invasion while STIM silencing shows anti-proliferative effects both in vitro and in vivo." (PMID 30597867, 2018). "Previous studies suggested that Stim1 as well as SOCE contributed cancer cell apoptosis in response to different chemotherapeutic drugs." (PMID 28326487, 2017). "Here we show that the invasive fronts of cancer tissues overexpress STIM1, accompanied by active store-operated Ca2+ entry (SOCE)." (PMID 28912430, 2017).
cancer (continued). "On the other hand, additional studies investigating STIM1 impact on cell migration speed using various cancer cell lines have reported opposite results, suggesting that STIM1 is an accelerator of migration speed." (PMID 28303257, 2017). "STIM1 overexpression markedly enhanced cervical tumor cell growth, local spread and angiogenesis and promoted cancer cell migration and invasion." (PMID 27863410, 2016). "STIM1 and Orai1 have also been demonstrated to play a role in cell migration and invasion in numerous cancers." (PMID 27417567, 2016). "Recently, several studies have demonstrated that Orai1 and STIM1 are involved in cancer progression." (PMID 26919241, 2016). "Based on this, reciprocal up-regulation of STIM1 suggests a compensatory or contributory role of STIM1 in the up-regulation of SOC entry in cancer cells." (PMID 27443843, 2016). "Recent studies have examined the significant role of STIM1 in the metastasis of various types of cancers." (PMID 26257076, 2015). "Significantly, STIM1 regulates cancer cell migration and invasion ability, and this concept was supported by our data, which showed a correlation between elevated STIM1 expression levels and an enhanced lymphatic invasion status in COAD patients." (PMID 26543234, 2015). "Heterogeneity in the cancer cell line or tumor is considered as a key reason; some cells underwent senescence when STIM1 was overexpressed, but those that survived gained the ability to metastasize by undergoing the EMT." (PMID 26257076, 2015). "Growing body of evidence indicates that SOCE in cancer cells is mediated by Stim1, which relays the information relative to the drop in ER Ca2+ levels to cell periphery, where it binds to and activates Orai1, a highly Ca2+-selective pore-forming unit." (PMID 25126575, 2014). "Recent studies have demonstrated an important role for ORAI1 and STIM1 proteins in cancer cells and carcinogenesis." (PMID 23922331, 2013). "Targeting the molecular components of SOCE, STIM1 and Orai1, is thus a promising approach to inhibit cancer cell migration and tumor metastasis." (PMID 23594099, 2013). "EGF, an important stimulator for cancer cells migration, can stimulate the aggregation and translocation of STIM1 towards to the Orai1-containing regions of plasma membrane to mediate SOCE." (PMID 23594099, 2013). "Aberrant expression of STIM1 and STIM2 proteins has been associated with human cancer but their direct role in tumorigenic events has yet to be established." (PMID 18950512, 2008). "STIM1 participates in processes such as cancer cell proliferation, migration, and angiogenesis." (PMID 40361464, 2025). "Reduced STIM1 levels have been associated with decreased mitochondria‐free Ca2+ and respiration, which suggests that the underlying molecular systems leading to increased SERCA ATPase activity upon cancer or changes in housing temperature are different." (PMID 40237521, 2025). "While these channels may contribute to calcium signalling in cancer, their involvement is distinct from the classical STIM1‐Orai1‐mediated SOCE pathway." (PMID 40952239, 2025). "It is widely accepted that the cancer‐promoting function of STIM1 is dependent on SOCE." (PMID 38344399, 2024). "Firstly, it may promote cancer cell proliferation through the activation of HIF1α, which leads to STIM1 puncta formation and SOCE activation, Secondly, it could activate mitochondrial autophagy, depending on the heterogeneity of the tumor." (PMID 39104527, 2024). "Knockdown of ORAI1 and STIM1 has also been shown to sensitize cancer cells to anti-cancer drugs." (PMID 38510751, 2024). "However, in several cancer types, it remains unexplored how Ca2+ entry via the STIM1/Orai1 machinery affects the various cell cycle effectors, either directly via Ca2+-binding proteins or indirectly via transcription factors, Ras/ERK, or PI3K/Akt pathways." (PMID 36612099, 2022).
cancer (continued). "Notably, the low expression of STIM1β in T and B cells makes it a more suitable anti‐cancer target than STIM1 to avoid potential side effects on the immune system." (PMID 35076181, 2022). "It remains to be determined whether these observations in dependence on STIM1 play a role in native tissue and cancer." (PMID 36612099, 2022). "However, in several tumor cells, upregulation of one or more of the CRAC channel components, mostly STIM1 and Orai1, promotes the development of cancer hallmarks." (PMID 36612099, 2022). "Interestingly, in cervical, colorectal, and liver cancer, only STIM1 has been detected to be critical, and in esophageal cancer, only Orai1 has so far been detected as such." (PMID 36612099, 2022). "STIM1 is involved in various diseases associated with dysregulation of SOCE including vascular disorders, neurodegenerative conditions, severe combined immunodeficiency syndrome, skeletal muscle disorders, and cancers." (PMID 36356899, 2022). "Moreover, elevated STIM1 and Orai1 expressions were thought to promote tumor cell proliferation in various cancers." (PMID 35669690, 2022). "Interestingly, a correlation between STIM1 and Orai1 expression and specific cell cycle regulators has been found in most cancers, providing targeted therapeutic options." (PMID 36612099, 2022). "Within these cancers one can find higher levels of STIM1 proteins than in healthy tissues." (PMID 35681544, 2022). "These suggested that STIM1-mediated SOCE contribute to tumorigenesis in some cancers." (PMID 33867841, 2021). "It was demonstrated that STIM1-mediated SOCE may play dual roles in types of cancer under the treatment of different anti-cancer drugs." (PMID 33867841, 2021). "We aimed to uncover the impact of different STIM1 variants on SOCE and cancer cell behavior." (PMID 34803742, 2021). "Similarly, increased SOCE in STIM1-overexpressing cancer cells renders them resistant to ER stress, while decreased STIM1 and SOCE levels promote ER stress in pancreatic β cells." (PMID 33919156, 2021). "In light of our in vitro findings, Ca2+ homeostasis may be an important factor that should be considered for the development of novel drugs targeting STIM1 for cancer treatment, and further in vivo study need to be performed in the future." (PMID 35008585, 2021). "Although STIM/ORAI1-mediated augmented SOCE has been reported to promote tumor growth and metastasis in many cancer types, STIM1 drives growth arrest in human rhabdomyosarcoma and rhabdoid tumor cell lines, ORAI1 facilitates apoptosis of PCa cells and the knockdown of ORAI1 leads to drug resistance." (PMID 34070562, 2021). "Some studies have proposed that STIM1-mediated SOCE facilitates cancer cell migration." (PMID 35008585, 2021). "We, thus, postulated that the malignant-derived STIM1 score (i.e. average value in bulky tissues) can be utilized as a surrogate for malignant-cell-specific functional activation of STIM1 expression in bulky cancer specimens." (PMID 33859736, 2021). "Cancer cells with metastatic ability showed higher STIM1 expression." (PMID 35008585, 2021). "STIM1 mutations result in alterations of Ca2+ influx, and subsequent cancer cell migration, which imply that STIM1 might be a potential prognostic marker and therapeutic target." (PMID 34803742, 2021). "Similarly, the presence of the dominant negative form of exogenous STIM1 also promoted cell migration, implying that cancer cells have the innate ability to regulate Ca2+ influx to benefit their survival." (PMID 35008585, 2021). "The in-depth understanding of STIM1 mediated SOCE may be an promising subject to improve effect in cancer therapy." (PMID 33867841, 2021). "We also describe some proteins associated with MCS, like CERT, STIM1, VDAC, and Orai, that impact on cancer progression and that could be a possible diagnostic marker." (PMID 33511135, 2020).
cancer (continued). "Moreover, inhibiting Stim1 and Orai1 results in the modulation of tumor migration, metastasis, and proliferation in other cancer cells." (PMID 32841278, 2020). "The overexpression of ORAI1 and STIM1 in tumor cells contributes to cancer growth." (PMID 32015442, 2020). "Moreover, STIM1 and Orai1 are upregulated in cancer cells and to trigger their development and growth." (PMID 33333945, 2020). "These previous findings suggest that STIM1 may have a dual role in regulating chemoresistance in different types of cancers." (PMID 31823522, 2020). "Whether the roles of STIM1 in the cancer microenvironment are tended to immune pathways or simply control cell cycle/cell growth is an important question to address in the future." (PMID 33348924, 2020). "Our tool can be further adapted into a high-throughput format to rapidly screen mutations in STIM1 that might decouple ORAI channel-binding from channel-gating, and to aid the functional characterization of a panel of cancer-associated STIM1 mutations." (PMID 32098964, 2020). "Indeed, previous research show that the role of STIM1 in regulation of cancer progression was controversial." (PMID 31564210, 2019). "Indeed, during human carcinogenesis, cancer cells overexpress STIM1 compared with normal epithelial cells." (PMID 31564210, 2019). "Thus, inhibiting STIM1-dependent Ca2+ signaling by specifically targeting STIM1 activation and translocation in cancer cells is a potential target for cancer therapy for breast, cervical, colon, prostate and hepatic cancer." (PMID 28494008, 2017). "STIM1 overexpression usually promote cancer procession and metastasis." (PMID 28494008, 2017). "Additionally, our results showed that the inhibition of STIM1-mediated Ca2+ signaling decreases podosome-mediated matrix degradation and cell invasion, supporting a role of STIM1-mediated Ca2+ signaling in malignant tumor progression." (PMID 28912430, 2017). "We studied the role of STIM1 in the formation of invadopodia in cancer cells." (PMID 28912430, 2017). "(d) Blockade of STIM1-mediated Ca2+ signaling inhibited cancer cell migration and invasion." (PMID 28912430, 2017). "Whether STIM1-dependent Ca2+ signaling facilitates cancer cell invasion through affecting podosome formation remains unclear." (PMID 28912430, 2017). "Hence, EGCG can be considered an epigenetic regulator of the key players accomplishing SOCE in murine CD4+ T cells, Jurkat T cells and other cancer cells, i.e. STIM1/2 and Orai1." (PMID 29163766, 2017). "ORAI1 and STIM1 regulate proliferation, apoptosis and metastasis of various cancer cells." (PMID 26789410, 2016). "Differential expression of STIM1 has been discovered in several human cancer cells." (PMID 27199756, 2016). "Therefore, in a variety of cancer types, both STIM1 and Orai1 were found to be upregulated and positively correlated to metastasis." (PMID 27417567, 2016). "This difference suggests that the effect of STIM1 on cell cycle regulation might be tissue- and cancer type- specific." (PMID 26257076, 2015). "Furthermore, although most recent research suggested a positive role of STIM1 on cancer cell motility, other reports revealed the opposite results in primary cells." (PMID 25977921, 2015). "The role of STIM1 in regulating cancer progression remains controversial." (PMID 23578185, 2013). "It is thus proposed that tumor STIM1 overexpression may benefit the locomotion and metastasis of cancer cells." (PMID 23594099, 2013). "Reflecting the eminent importance of CRAC current following receptor stimulation, several recent studies addressed the role of Orai1/STIM1 in chemotactically or chemokinetically stimulated migration with a particular focus on cell adhesion both in cancer cells as well as in vascular endothelium." (PMID 24204345, 2013). "Blocking Orai1- and STIM1-dependnet Ca2+ signaling is thus a potential strategy for cancer therapy." (PMID 23594099, 2013).
cancer (continued). "Thus, the mScarlet-C-SARAF fragments could interact directly with STIM1, regulating its conformational change, which may result in reduced cell migration and the invasion of cancer cells." (PMID 36982380, 2023). "Additionally, it has been claimed that SOCE could play a role in the oncogenic pathway, since its blockage, which can be achieved through the knockdown of STIM1 or Orai1, prevents the proliferation and spread of cancer cells." (PMID 37259313, 2023). "Therefore, it seems that the post-translational modifications of Stim1 and Orai1 play a role in (cancer) cell migration and polarized plasma membrane organization, as demonstrated by several groups through RNA interference, gene-knock-out, or Stim1 overexpression systems." (PMID 35254656, 2022). "In addition, STIM1 can regulate the secretion of VEGF-A by cancer cells." (PMID 36230965, 2022). "Therefore, we attempted to clarify whether the cancer migration ability is influenced by the STIM1-mediating SOCE response." (PMID 35008585, 2021). "The STIM1 mediated SOCE activation also involved in this process, and the knockdown of STIM1 or pharmacological inhibition of SOCE can reversed anti-cancer effect of DIM by inhibiting p-AMPK-mediated ER stress, indicating that STIM1 mediated SOCE might be a critical step for DIM induced cells death." (PMID 33867841, 2021). "Thus, we investigated the effects of STIM1 or ORAI1 knock-down on ML-1 cancer cell invasion." (PMID 34155535, 2021). "Hence, targeting STIM1 to manipulate Ca2+ homeostasis may be a promising strategy to prevent cancer metastasis." (PMID 35008585, 2021). "STIM1 is known to express highly in several cell types (e.g. fibroblasts 16) that may exist within cancer tissues 17 Recent technical and analytical advances allow us to dissect STIM1 expression and enables a detailed examination of cell-specific cellular programs within the tumor microenvironment." (PMID 33859736, 2021). "Therefore, the direct correlation between STIM1 protein expression level and ITPR3 expression found here may explain the suggested correlation between STIM1 protein levels and proliferation and malignancy in cancer cells." (PMID 32916960, 2020). "Furthermore, STIM-1 enhances cell migration and promotes metastasis of cancer cells." (PMID 32098295, 2020). "Indeed, overexpression of STIM1 has been shown to promote cancer progression." (PMID 33348924, 2020). "Consequently, some cancers upregulate STIM-1 and ORAI-1 or ORAI3 to ensure a steady supply of low- to mid-level calcium, and cancer cells may become calcium-dependent." (PMID 29758025, 2018). "The Orai1 and STIM1 inhibition could offer novel anti-cancer therapeutic strategies." (PMID 29861863, 2018). "It applauses the possibility that STIM2 may replace STIM1 to couple with Orai1 in cancer cells." (PMID 24797725, 2014). "Aberrant expression of STIM1 could be observed in several human cancer cells." (PMID 23578185, 2013). "Store-operated calcium entry (SOCE), mediated by ORAI1-3 calcium channels and stromal interaction molecules STIM1 and STIM2, is increasingly recognized as a regulator of cancer progression." (PMID 41801973, 2026). "Previous studies have shown that the endoplasmic reticulum (ER) Ca2+ sensors, stromal interaction molecules STIM1 and STIM2, are key regulators of cancer cell migration." (PMID 40719699, 2025). "Store-operated calcium entry (SOCE), involving components such as STIM1, Orai1, and SARAF, plays a critical role in calcium signaling and cancer progression." (PMID 40362663, 2025). "Despite, the limited data regarding the possible oncogenic role of STIM1 in PDAC and AAC, previous studies have postulated the potential oncogenic role of STIM1 in many cancers." (PMID 38532463, 2024). "SOCE is the major influx of Ca2+ in non-excitable cells, however, high expression of STIM1, ORAI1, and activated SOCE were found to be involved in cancer progression, migration, and metastasis for cervical cancer, breast cancer and hepatocarcinoma." (PMID 38903530, 2024).